GPC2 (glypican 2)
Diseases named in the same sentence as GPC2 in open-access papers (continued):
Sharing a sentence is not in itself a finding about the gene and the disease.
Hydrocephalus (1 paper, 2023). Hydrocephalus is an active distension of the ventricular system of the brain resulting from inadequate passage of CSF from its point of production within the cerebral ventricles to its point of absorption into the systemic circulation. "It is most likely that the association between CSF-DCX/GPC2 and hydrocephalus is due to a confounding effect of age." (PMID 36800341, 2023). "CSF-DCX and GPC2 were associated with hydrocephalus, a condition characterized by an excess of CSF and causing an enlargement of the ventricles." (PMID 36800341, 2023). "Both DCX and GPC2 associated with hydrocephalus, NSE, IL-1β, IL-2, IL-8, IL-13." (PMID 36800341, 2023).
myeloma (1 paper, 2012). "Furthermore the expression of mRNA encoding glypican-2 was found in all the cell lines, except for the myeloma cell line U-266." (PMID 22777011, 2012).
non-small cell lung carcinoma (1 paper, 2022). A group of at least three distinct histological types of lung cancer, including non-small cell squamous cell carcinoma, adenocarcinoma, and large cell carcinoma. "The intersection of the two was taken to screen five non-small cell lung cancer signature genes from the training sets GSE151103 and GSE33532: DOCK6, GPC2, RHEBL1, RNPC3, and PIWIL2." (PMID 36386821, 2022).
Obesity (1 paper, 2022). Accumulation of substantial excess body fat. "In the present study, growth-related genes, GAL, CENPF, and GPC2, obesity-related gene, PEMT, and CYP3A4, P450, TMEM200B genes were found to be associated with BWF." (PMID 35795788, 2022).
oral cancer (1 paper, 2024). "Whatmore, one-way Cox regression analysis showed that three BMGs, LAMA3, MMP14, and GPC2, were significant prognostic predictors in oral cancer patients." (PMID 38877482, 2024).
pancreatic adenocarcinoma (1 paper, 2022). "The results indicated that GPC2 was highly expressed in most cancers, except in pancreatic adenocarcinoma, which presented at a quite low level." (PMID 35345673, 2022). "In contrast, GPC2 had a low expression in tumor relative to normal tissues in pancreatic adenocarcinoma (PAAD)." (PMID 35345673, 2022).
pancreatic ductal adenocarcinoma (1 paper, 2024). An infiltrating adenocarcinoma that arises from the epithelial cells of the pancreas. "In early-stage pancreatic ductal adenocarcinoma (PDAC), GPC2 expression was higher in tumor tissues when compared to adjacent normal tissues." (PMID 39014225, 2024).
psychological distress (1 paper, 2019). "We also assessed genetic correlations between the GQ psychological distress results and other GWAS results including CONVERGE MDD, PGC2 MDD, and GPC2 neuroticism results." (PMID 30705256, 2019).
retinoblastoma (1 paper, 2021). A malignant tumor that originates in the nuclear layer of the retina. "We also found strong GPC2 staining in 78% of retinoblastoma (RB) tissues (7/9), but none in the non-cancerous sclera or retina samples." (PMID 34195677, 2021).
urothelial carcinoma (1 paper, 2021). A malignant neoplasm derived from the transitional epithelium of the urinary tract (urinary bladder, ureter, urethra, or renal pelvis). "However, the role of GPC2 and SETBP1 in urothelial carcinoma is not certain due to the lack of sufficient studies." (PMID 34315402, 2021).
uterine carcinosarcoma (1 paper, 2022). A usually aggressive malignant neoplasm arising from the uterine corpus and less often the cervix. "GPC2 was expressed in all tumors, with the highest level in uterine carcinosarcoma (UCS) and, conversely, lowest in liver hepatocellular carcinoma (LIHC)." (PMID 35345673, 2022).
tumor (39 papers, 2012 to 2026). "The diminished cytotoxic activity was associated with decreased GPC2 expression in the surviving tumor cell population." (PMID 41159102, 2025). "An additional example is a CAR containing the scFv of the anti-GPC2 mAb (CT3) recognizing tumor-associated epitopes of GPC2." (PMID 36231134, 2022). "exploit RNA-seq data to identify tumor-associated exons of glypican 2 (GPC2) that can be targeted by a monoclonal antibody (CT3)." (PMID 34195677, 2021). "In the present study, we developed a strategy to identify tumor-associated exons (exons 3 and 7–10) in GPC2 by RNA-seq analysis and determined that exon 3 is rare in normal tissues but prominently expressed in cancer (NB)." (PMID 34195677, 2021). "We then identified a monoclonal antibody (mAb), which we called CT3, that recognizes tumor-associated exons 3 and 10 of GPC2." (PMID 34195677, 2021). "We used an exon-based RNA sequencing (RNA-seq) analysis to identify “tumor-associated exons” of GPC2." (PMID 34195677, 2021). "We also investigated GPC2 from the aspects of methylation level, immunohistochemical analysis, and mutation analysis, which will be helpful to further elucidate the mechanism of GPC2 in tumor development in the future." (PMID 35345673, 2022). "The mutation of the GPC2 gene in all tumor tissues was analyzed by the cBioPortal platform." (PMID 35345673, 2022). "In conclusion, we report an antibody (CT3) that recognizes tumor-associated exons on GPC2." (PMID 34195677, 2021). "Interestingly, the authors reported the identification of a tumor-associated GPC2 mRNA variant." (PMID 36231134, 2022). "GPC2-CARs lead to significant in vivo tumor regression in orthotopic tumor models via intravenous or intraventricular administration route and had equivalent activity to the B7-H3-CAR against D283 and enhanced activity than GD2-CAR in both models in vivo." (PMID 41159102, 2025). "To investigate the infiltration of T cells in tumor tissues, we employed immunohistochemistry (IHC) staining to detect the expression of antigen (GPC2) and CD3+ T cells in tissue sections from the LAN1 mouse model." (PMID 41027430, 2025). "The GPC2-CAR induced a more rapid tumor response than the B7-H3-CAR as early as 7 days after CAR T cell injection." (PMID 41159102, 2025). "T cell kinetic studies revealed that GPC2-CAR T cells home to the area of the primary tumor, expand, and upregulate genes critical for cytotoxicity and T cell recruitment." (PMID 41159102, 2025). "T cell kinetic studies revealed that GPC2-CAR T cells home to the area of the primary tumor, expand, and upregulate genes critical for cytotoxicity and T cell homing." (PMID 41159102, 2025). "In both models, treatment with GPC2- and B7-H3-CARs led to the most pronounced tumor regression by IVIS BLI." (PMID 41159102, 2025). "B7-H3-specific CAR T cell therapies have shown promising results in xenograft models, while dual CAR approaches targeting both B7-H3 and GPC2 have been proposed to address tumor heterogeneity more effectively." (PMID 39860532, 2025). "Repeated testing of CAR constructs has shown that a CAR composed of a single chain variable fragment (scFv) derived from an antibody that targets GPC2 (CT3) exhibits superior anti-tumor activity against HRNB." (PMID 40104501, 2025). "GPC2 was upregulated in tumor tissues and correlated with clinical stage, tumor metastasis, and patients’ prognosis." (PMID 39014225, 2024). "Another promising target against which ADCs have been developed is the oncoprotein GPC2, which is overexpressed in neuroblastoma and drives tumor cell proliferation." (PMID 38087370, 2023). "Given the low GPC2 expression by health tissues, on-target off-tumor toxicity by CAR T cells with engineered high antigen sensitivity is a clinically crucial issue." (PMID 38090558, 2023).
tumor (continued). "While GPC1 and GPC2 exhibited a strong net upregulation in tumor samples over normal across the board of cancer types, other members like GPC4, GPC5, and GPC6 were characterized by tissue-specific cancer expression patterns." (PMID 36944188, 2023). "They discovered that GPC2 antigen density was below the threshold required for anti-tumor efficacy in traditional GPC2-CAR-T cells and modified them using CD28 co-stimulatory endodomains." (PMID 36853475, 2023). "Alongside T cells, macrophages have emerged as major mediators of the anti-GPC2 ADC treatment, and the combination of anti-GPC2 ADCs with anti-CD47 blockade has demonstrated a modest reduction in tumor burden." (PMID 38087370, 2023). "Recent reports of tumor IHC have implied variable inter- and intratumoral expression of GPC2 and CD276 in NB." (PMID 35852863, 2022). "The results showed that the expressions of GPC1 and GPC2 were higher (P<0.001) in CRC tissues than non-tumor tissues." (PMID 35671267, 2022). "Together, these data demonstrated that the BiCisCAR had longer persistence and was less prone to exhaustion in the tumor model with heterogeneous expression of GPC2 and CD276." (PMID 35852863, 2022). "This predicts that GPC2 is a good indicator that can reveal the occurrence of cancer in vivo from the side and play a very good supporting role in the diagnosis of tumor." (PMID 35345673, 2022). "GPC2/CD276 BiCisCAR exhibits superior antitumor activity to tumor cells expressing either GPC2 or CD276." (PMID 35852863, 2022). "Glypican 2 (GPC2) is over-expressed on NB cells, and it is a target for the tumor delivery of drugs in the form of immunoconjugates." (PMID 36231134, 2022). "By understanding the relationship between GPC2 gene expression and the level of tumor immune cell infiltration, we can find that the expression of GPC2 is mostly negatively correlated with the level of immune cell infiltration." (PMID 35345673, 2022). "To put it in a nutshell, we found that GPC2 was widely differentially expressed between tumor tissues and normal tissues through pan-cancer analysis and revealed the correlation between GPC2 expression and clinical prognosis." (PMID 35345673, 2022). "However, when CAR T cells were repeatedly challenged with tumor cells, GPC2-CARs showed reduced cytotoxicity compared to GD2- and B7-H3-CARs, particularly against D283 cells." (PMID 41159102, 2025). "Interestingly, the response kinetics of each CAR were different, with GPC2-CAR T cells inducing the most rapid tumor regression within the first 7 days in the MAF1433 model." (PMID 41159102, 2025). "In mice, agonist anti-CD40 mAb can augment the anti-tumor efficacy of an anti-GPC2 antibody drug conjugate via macrophage activation, and can also facilitate the induction of anti-survivin reactive T cells that kill slightly immunogenic NBLs, likely via antigen-presenting cell activation." (PMID 38731089, 2024). "GPC2.28ζ-GLUT1 also improved tumor clearance of NGP-GPC2 cells across multiple E:Ts." (PMID 39370422, 2024). "Several of the other GPC2-targeting CAR constructs also showed tumor-killing ability." (PMID 35852863, 2022). "BiCisCAR T cells effectively eliminated tumor cells expressing GPC2 or CD276." (PMID 35852863, 2022). "Besides, a noteworthy increase in GPC2 expression in 16 types of cancer was observed respectively in paired tumor samples compared with corresponding normal samples." (PMID 35345673, 2022). "Glypican-2 (GPC2) has been reported to promote tumor progression through metabolic pathways." (PMID 35233466, 2022). "Therefore, GPC2 can be used as an auxiliary indicator for early tumor diagnosis and a prognostic marker for many types of tumors." (PMID 35345673, 2022). "One such example could be the delivery of DNA-damaging pyrrolobenzadiazepine (PBD) dimers with applications of the D3-GPC2-IgG1 mAb that recognizes a tumor-specific epitope of GPC2." (PMID 36231134, 2022).
tumor (continued). "Furthermore, the analysis results of tumor immune cell infiltration level and immune-related genes also showed that the expression level of GPC2 was mostly positively correlated with immune-related expression level." (PMID 35345673, 2022). "Our findings suggest that GPC2 has the potential to become an independent prognostic factor for many tumors and that the level of GPC2 expression may vary in different types of tumor." (PMID 35345673, 2022). "The specific role of GPC2 in each tumor needs to be further studied." (PMID 35345673, 2022). "In addition, the performance of GPC2 in tumorigenesis and tumor immunity also confirms our conjecture." (PMID 35345673, 2022). "We hypothesized that exon 3 and C-terminal subunit exons 7–10 could be tumor-enriched epitopes for GPC2." (PMID 34195677, 2021). "In addition, GD2 and GPC2 (CT3) CAR T cells induced comparable levels of tumor cell killing and cytokine production following exposure to IMR5 cells." (PMID 34195677, 2021). "Unlike previously validating the two higher-affinity GPC2 CARs19, the clone we chose had failed in targeting lower antigen density targets and we wanted to determine if it could achieve effective tumor targeting in DIPG given the high level of GPC2 detected in our proteomics." (PMID 40517137, 2025). "GPC2-CAR T cells comprised the lowest proportion at that time, possibly because tumor clearance has already occurred." (PMID 41159102, 2025). "The largest cell cluster was composed of tumor cells, followed by CAR T cells, among which B7-H3-CAR T cells being the most abundant (1,693 cells), followed by GD2-CARs (891 cells) and GPC2-CARs (231 cells)." (PMID 41159102, 2025). "GPC2-directed CAR T cells demonstrated early and sustained activation in tumor co-culture, with increased intracellular interferon (IFN)-γ detected at 12 h and elevated granzyme B (GZMB) levels by 36 h." (PMID 41159102, 2025). "Our study shows that MB patient samples express up to moderate levels of GPC2 and can be targeted with a GPC2-CAR, leading to significant in vivo tumor regression in orthotopic cell line and PDX cell line models." (PMID 41159102, 2025). "In the D283 model, B7-H3-CARs induced a rapid tumor decrease in tumor size by day 14 post-CAR injection, while GPC2-CARs triggered a more gradual reduction over 3–4 weeks." (PMID 41159102, 2025). "GPC2/CD276 BiCisCAR showed superior antitumor activity in vivo in animal testing, in which 33.3% of mice showed good tumor suppression or even tumor elimination activity." (PMID 38090056, 2023). "The GPC2-targeting CAR, CT3, has density-dependent killing property, so it is also likely to have minimal on-target/off-tumor toxicity to normal tissues." (PMID 35852863, 2022). "Of the 16 metabolism-related genes, we found AOC2, IDUA, GPC2, CSPG4, TPST1, and CYP1B1 to be differentially expressed between tumor and normal tissues at the protein level." (PMID 35281080, 2022). "Of the 16 metabolism-related genes, we found that AOC2, IDUA, GPC2, CSPG4, TPST1, and CYP1B1 were differentially expressed between tumor and normal tissue at the protein level according to the Human Protein Atlas (HPA) cohort." (PMID 35281080, 2022). "From the heat map, we can intuitively see that almost all immune-related genes were co-expressed with GPC2, and except LUSC and SARC, majority of immune-related genes were positively correlated with GPC2 in all types of tumor (p < 0.05)." (PMID 35345673, 2022). "Interestingly, tumor and normal tissues express different GPC2 transcripts, indicating the possible existence of highly tumor-selective GPC2 sequences that may be useful for GPC2-targeted immunotherapies." (PMID 34195677, 2021). "Mice treated with hCT3 AbTCR T cells showed a significantly reduced tumor burden and a comparable survival curve compared to the CT3 CAR group by day 35 (p < 0.05), suggesting that hCT3 AbTCR T cells are ideal for treating low-GPC2-antigen-density tumors." (PMID 41027430, 2025).
tumor (continued). "To assess the therapeutic potential of GPC2-targeted CAR T cells in DIPG, and to validate the target discovery pipeline, we selected the lowest-affinity GPC2 CAR construct to minimize on-target/off-tumor toxicity while maintaining tumor specificity." (PMID 40517137, 2025). "After flank tumor establishment, mice were treated with an intravenous dose of GPC2 CAR T-cells, or CD19 CAR T-cells as negative control." (PMID 39908652, 2025). "As anticipated, human donor-derived GPC2-directed CAR T cells demonstrated significant antigen-specific tumor cell killing relative to negative control donor matched untransduced T cells or target cells alone." (PMID 40517137, 2025). "To evaluate the activity of GPC2-CAR T cells in vivo, we stereotactically implanted D283 or MAF1433 into the cerebellum of NOD SCID gamma (NSG) mice (4–6 weeks old), which establishes orthotopic tumor." (PMID 41159102, 2025). "As anticipated, human donor-derived GPC2-directed CAR T cells demonstrated significant antigen-specific tumor cell killing relative to negative control donor-matched CD19 CAR T cells, untransduced T cells or target cells alone." (PMID 40517137, 2025). "In this study, 95% of NB samples had high expression of GPC2 and CD276, and CT3 and MGB7H3‐LH were confirmed to be effective CAR constructs for recognizing GPC2‐ and CD276‐expressing tumor cells using multimodal single‐cell analysis methods and cytotoxicity assays." (PMID 38090056, 2023). "Given the heterogeneity of GPC2 and CD276 on NB cells, targeting only 1 antigen may be ineffective at eliminating the tumor, leading to immune evasion." (PMID 35852863, 2022). "In our study, an elevated methylation level of the GPC2 promoter and a high expression level of GPC2 appeared simultaneously, which is not uncommon in tumor tissues." (PMID 35345673, 2022). "Earlier studies had found that glypican-2 (GPC2) and GPC3 are highly specific for tumor tissues." (PMID 35233466, 2022). "To model the heterogenous expression of GPC2 and CD276, which can result in tumor evasion in single-target CAR T cell therapies, we used a mixture of NALM6 cells stably expressing either GPC2 or CD276 and treated them with BiCisCARs or single antigen–targeting CARs." (PMID 35852863, 2022). "Additionally, GPC2-CAR T cells did not exert cytotoxic effects on GPC2-negative targets, indicating that tumor cell killing is antigen-dependent." (PMID 41159102, 2025). "In our study, GPC2-CAR T cell-treated mice tolerated treatment and had elevated levels of immune-suppressive interleukin-10 in their serum after tumor clearance, though these observations in xenograft mouse models may not accurately predict on-target off-tumor toxicities in the clinic." (PMID 41159102, 2025). "However, the purities of GPC2 tumor did not significantly differ from those of GPC1 based on comparable variant allele frequency (VAF) distribution, which suggests that the abundance of normal cells in tumors does not contribute to these proteomic differences." (PMID 32620753, 2020). "However, no on-target off-tumor toxicity by c-Jun overexpressing GPC2 CAR T cells was recorded." (PMID 38090558, 2023). "In NB-PDX mouse models treated with a GPC2-targeting ADC (D3-GPC2-PBD) for 20 weeks, no tumor recurrence or weight changes were observed." (PMID 40129921, 2025). "As expected, single antigen–specific CAR T cells could not suppress tumor growth, although the GPC2 single CAR performed slightly better than did the CD276 single CAR because of the low expression levels of GPC2 in the CD276-overexpressing NALM6 cells." (PMID 35852863, 2022). "Furthermore, GPC2 and CD276 expression levels were independent of the tumor’s MYCN amplification status." (PMID 35852863, 2022). "Moreover, the expressions of GPC-1, GPC-2, GPC-4, GPC-5, and GPC-6 were not significantly different between tumor and normal liver tissues." (PMID 33902495, 2021).